YTHDF2 (YTH N6-methyladenosine RNA binding protein F2)
Diseases named in the same sentence as YTHDF2 in open-access papers (continued):
Sharing a sentence is not in itself a finding about the gene and the disease.
ocular melanoma (continued). "In ocular melanoma, a lactylation increase in H3K18 sites at the YTHDF2 promoter region improved YTHDF2 expression and sustained ocular melanoma malignization." (PMID 37760477, 2023).
prostate carcinoma (42 papers, 2018 to 2025). A carcinoma that arises from epithelial cells of the prostate gland. "MiR‐493‐3p directly targets YTHDF2, reducing its expression and suppressing prostatic carcinoma cell proliferation." (PMID 39135292, 2024). "Specifically, miR-493-3p enhances m6A levels by downregulating YTHDF2, significantly inhibiting prostate cancer cell proliferation and migration." (PMID 39596416, 2024). "YTHDF2 interacts with miRNAs and influences the migration and invasion capabilities of prostate cancer cells." (PMID 39372951, 2024). "In prostate cancer, the higher the expression of METTL3 and YTHDF2, the lower the survival rate of prostate cancer patients." (PMID 37701836, 2023). "Previous studies demonstrated that YTHDF2 regulated the Akt or NF‐κB pathways in prostate cancer or GBM through facilitating relevant gene mRNA degradation." (PMID 35582627, 2022). "KDM5A can also promote the progression of prostate cancer through the KDM5A/miRNA-495/YTHDF2/m6A-MOB3B axis." (PMID 35493099, 2022). "have claimed that YTHDF2 mediates the mRNA degradation of the tumor suppressor LHPP to induce AKT phosphorylation in prostate cancer." (PMID 35582627, 2022). "It was reported that YTHDF2 was overexpressed in both bladder cancer and prostate cancer (PCa) and was remarkably downregulated in clear cell renal cell carcinoma (ccRCC)." (PMID 35382893, 2022). "For example, YTHDF2 was upregulated in prostate cancer, and YTHDF2 knockdown impaired prostate cancer proliferation, migration, and invasion." (PMID 36439881, 2022). "The oncogenicity of YTHDF2 was revealed in prostate cancer, and YTHDF2 mediates the degradation of LHPP and NKX3-1 to induce the phosphorylation of AKT112." (PMID 33795663, 2021). "YTHDF2 was found frequently up-regulated in prostate cancer through immuno-histochemical (IHC) staining and chromogenic in situ hybridization (CISH)." (PMID 33928028, 2021). "In the study of YTHDF2, researchers found that YTHDF2 was frequently overexpressed in prostate cancer and YTHDF2 knockdown elevated m6A level and retained tumor cell proliferation and migration with the up-regulated miR-493-3p." (PMID 33593354, 2021). "Above results suggest that YTHDF2 acts as an oncogene in prostate cancer and YTHDF2 is expected to be a potential biomarker for diagnosis or targeted therapy of prostate cancer." (PMID 33928028, 2021). "This study was performed to elucidate the potential effects of KDM5A on prostate cancer (PCa) progression via the miR-495/YTHDF2/m6A-MOB3B axis." (PMID 33087165, 2020). "VIRMA and YTHDF2 play vital roles in prostate cancer, the second most common diagnosed cancer in men." (PMID 32612834, 2020). "The carcinogenesis of METTL3 and YTHDF2 in prostate cancer and bladder cancer mainly contributes to the inhibition of antitumour genes and the promotion of oncogenes, resulting in tumour development." (PMID 32808488, 2020). "As crucial m6A regulators, METTL3 and YTHDF2 act as oncogenes in both prostate cancer and bladder cancer." (PMID 32808488, 2020). "The expression of YTHDF1/2 is elevated in bladder cancer, and the expression of YTHDF2 is elevated in prostate cancer." (PMID 32808488, 2020). "In our previous study, we found that the expression of YTHDF2 in prostate cancer was up‐regulated, and the increased expression of YTHDF2 was related to prostate cancer proliferation and metastasis." (PMID 32808488, 2020). "In prostate cancer, reduced YTHDF2 elevates m6A contents dramatically, which suppresses proliferation and migration." (PMID 32303268, 2020). "We presented IGF2BP3, HNRNPA2B1 and METTL14 were significantly related to RFS of prostate cancer based on mRNA expression information, while in the CNV-based regression model, YTHDF2, FTO, and ALKBH5 were notably associated with prognosis of prostate cancer." (PMID 32710725, 2020). "Knockdown of YTHDF2 inhibits the proliferation of prostate cancer cells, suggesting YTHDF2 has an oncogenic role." (PMID 32612834, 2020).
prostate carcinoma (continued). "Additionally, miR-493-3p has been identified as a direct upstream factor of YTHDF2, capable of inhibiting the proliferation and migration of prostate cancer cells." (PMID 39596416, 2024). "Additionally, in prostate cancer, miR-493-3p directly targets and reduces YTHDF2 levels to increase downstream m6A levels, thereby inhibiting the proliferation and migration of prostate cancer cells." (PMID 39062595, 2024). "On the other hand, amplification of YTHDF2 might disrupt with miR-495 suppressive effects on growth, aggression, and movement of prostate cancer cells as well as its triggering of apoptosis." (PMID 38125749, 2023). "Moreover, the positive expression of YTHDF2 in prostate cancer patients manifested a high tumor grade." (PMID 35382893, 2022). "Knockdown of YTHDF2 inhibited the proliferation and migration of prostate cancer cells." (PMID 33928028, 2021). "However, the function and mechanisms of m6A especially YTHDF2 in prostate cancer (PCa) still remain elusive." (PMID 33121495, 2020). "Future studies could highlight the broad potential of targeting METTL3 and YTHDF2 for both prostate cancer and bladder cancer." (PMID 32808488, 2020). "However, YTHDF2 has been discovered in prostate cancer which can promote cell proliferation and migration." (PMID 33134160, 2020). "Small‐molecule METTL3 and YTHDF2 inhibitors could be designed and synthetised to examine the antitumour effects and safety in both prostate cancer and bladder cancer." (PMID 32808488, 2020). "YTHDF1 and YTHDF2 play critical roles in both bladder cancer and prostate cancer." (PMID 32808488, 2020). "The up‐regulation of YTHDF2 in prostate cancer was possibly contributed to the regulation of miR‐493‐3p, which increased the m6A level and inhibited tumour carcinogenesis by down‐regulating its downstream target YTHDF2 in prostate cancer." (PMID 32808488, 2020). "However, the functions and mechanisms of YTHDF2 and the indirect m6A regulated role of miR-493-3p in prostate cancer (PCa) remains to be elusive." (PMID 29423080, 2018). "Similarly, miR-495 has YTHDF2 as a target gene, which it may use to interfere with the production of YTHDF2 in prostate cancer cells." (PMID 38125749, 2023). "Conversely, the expression levels of the other two YTHDF family members, YTHDF2 and YTHDF3, were reduced in prostate cancer." (PMID 40251202, 2025). "YTHDF2 mediates the mRNA degradation of the tumor suppressors LHPP and NKX3-1 in a METTL3-dependent manner to regulate AKT phosphorylation-induced prostate cancer progression." (PMID 38281945, 2024). "For example, YTHDF2 mediates mRNA degradation of tumor suppressors and induces AKT phosphorylation in an N6-methyladenosine-dependent way in prostate cancer." (PMID 39281280, 2024). "Seven m6A methylation-related genes (ALKBH5, FMR1, IGFBP3, RBM15B, YTHDF1, YTHDF2, and ZC3H13) were identified as cross-talk genes between prostate cancer and PD." (PMID 36133437, 2022). "Another study had the similar results, YTHDF2 mediated the degradation of tumor suppressors LHPP and NKX3–1 mRNA and indirectly induced AKT phosphorylation to promote prostate cancer progression in an m6A-dependent manner." (PMID 33928028, 2021). "YTHDF2 has been known to mediate the mRNA degradation of NKX3.1 and LHPP in an m6A-dependent way to regulate AKT phosphorylation-induced prostate cancer progression." (PMID 34899855, 2021). "Considering oncogenic role in prostate cancer and bladder cancer, METTL3 and YTHDF2 present opportunities for the development of effective targeted therapeutics." (PMID 32808488, 2020). "In prostate cancer, m6A modification level was upregulated, and the expression levels of METTL3, METTL14, VIRMA, RNA binding motif protein 15 (RBM15), HNRNPC, HNRNPA2B1, YTHDC2, YTHDF1 and YTHDF2 increased." (PMID 37701836, 2023).
prostate carcinoma (continued). "In summary, we provided in vitro and in vivo evidence to elucidate that YTHDF2 mediates the mRNA degradation of the tumor suppressors LHPP and NKX3–1 in m6A-depnedent way to regulate AKT phosphorylation-induced tumor progression in prostate cancer." (PMID 33121495, 2020). "We propose a novel regulatory mechanism in which YTHDF2 mediates the mRNA degradation of the tumor suppressors LHPP and NKX3–1 in m6A-dependent way to regulate AKT phosphorylation-induced tumor progression in prostate cancer." (PMID 33121495, 2020). "Notably, YTHDF1 exhibits high expression levels in colorectal adenocarcinoma, lung adenocarcinoma (LUAD) and colorectal adenocarcinoma tissues, while YTHDF2 is notably up‐regulated in breast cancer (BRCA), head and neck squamous cell carcinoma (HNSC), LUAD and prostate cancer (PRAD)." (PMID 39135292, 2024). "However, the expression patterns of the other four genes (ALKBH5, RBM15B, YTHDF1, and YTHDF2) in prostate cancer and periodontitis were not consistent." (PMID 36133437, 2022). "Overexpressed YTHDF2 could reverse the inhibitory role of miR-495 and decreased the m6A levels of mps one binder kinase activator 3B (MOB3B) to promote the proliferation and migration of prostate cancer cells." (PMID 35382893, 2022).
breast carcinoma (37 papers, 2019 to 2026). "Another study exploring RNA-binding proteins identified YTHDF2 as a driver of cell death in MYC-driven breast cancer given that loss of YTHDF2-dependent mRNA degradation induces apoptosis in TNBC." (PMID 40650785, 2025). "To date, METTL3, ALKBH5, FTO, and YTHDF2 have been implicated in promoting breast cancer tumorigenesis by affecting cancer cell survival/proliferation and cancer stem cell pluripotency 23-26." (PMID 35966596, 2022). "b Measurement of BNIP3 mRNA expression level by overexpression of YTHDF2 in FTO-deficient breast cancer cells." (PMID 30922314, 2019). "GDF11, CD151, PAFAH1B2 and YTHDF2 may play a pivotal role in the predisposition of metastasis to the bone from breast cancer, whilst DPP9, FAS, ZNF519, RPP14 and FAU may be actively involved in the adaptative colonisation of metastatic breast cancer cells in bone." (PMID 35685372, 2022). "The decreased m6A impedes YTHDF2-mediated degradation of YAP1 to enhance the tumor cell stemness in breast cancer." (PMID 40822927, 2025). "ALKBH5 drives glycolysis in resistant breast cancer cells by mediating YTHDF2-dependent m6A demethylation of GLUT4 mRNA, which stabilizes the transcript and enhances glucose metabolism." (PMID 40986143, 2025). "With eCLIP, m6A sequencing, and single‐cell Ribo‐STAMP (scRibo‐STAMP), they further explored alterations in the translatome at a single‐cell level within YTHDF2‐depleted solid tumors and highlighted the therapeutic potential of YTHDF2 in breast cancers." (PMID 39392204, 2024). "Analysis of YTHDF2 cross-linking and immunoprecipitation datasets across multiple breast cancer cell lines showed that the binding signals of YTHDF2 covered the m6A-specific peak around the stop codon of YAP1." (PMID 39563370, 2024). "In this case, decreased m6A methylation at the 5′‐UTR region of the transcription factor ATF3 mRNA and YTHDF2 downregulation in the breast cancer cells enhances the stabilization and translational efficiency of ATF3 transcripts." (PMID 39661414, 2024). "Here, we demonstrated that LATS1 mRNA m6A modification mediated by METTL3 and recognized by YTHDF2, plays a positive role in promoting both tumorigenesis and glycolysis in breast cancer." (PMID 36609396, 2023). "Specifically, METTL3/LATS1/YTHDF2 axis promotes glycolysis and tumorigenesis of breast cancer by inhibiting YAP/TAZ in Hippo pathway." (PMID 37582735, 2023). "Transcription factor 3 (ATF3) was highly expressed in tamoxifen-resistant breast cancer, and was regulated by low expression of YTHDF2." (PMID 35721510, 2022). "FTO mediated m6A demethylation in a YTHDF2-dependent manner and promoted the proliferation and metastasis of breast cancer via inhibiting BCL2 interacting protein 3 (BNIP3)." (PMID 35721510, 2022). "Moreover, data from TCGA also showed that YTHDF2 was significantly increased in ER+ breast cancer tissues relative to ANT." (PMID 40641925, 2025). "Importantly, YTHDF2 suppression induces proteotoxicity-driven cell death in MYC-overexpressing breast cancer." (PMID 40986143, 2025). "YTH domain family, member 2 (YTHDF2) inhibits the MYC-driven cell death in breast cancer cells." (PMID 39516455, 2024). "However, the protein level of LATS1 was inversely correlated with the expression of YTHDF2 in breast cancer cells." (PMID 36609396, 2023). "The expression of YTHDF2 in breast cancer cells promoted tumorigenesis both in vitro and in vivo." (PMID 36609396, 2023). "The seahorse assay showed that YTHDF2 had a positive effect on glycolysis in breast cancer cells." (PMID 36609396, 2023). "Reduced YTHDF2 may facilitate cancer cell homing, osteoclastogenesis and immune escape in breast cancer." (PMID 35685372, 2022). "Similarly, increased YTHDF2 expression was observed in many different tumour tissues, such as breast carcinoma, colon carcinoma, ovarian carcinoma and uterine corpus endometrial carcinoma, in the CPTAC database." (PMID 35186724, 2022).
breast carcinoma (continued). "In addition to these passenger mutations, we find SV events involving mobile elements that disrupt the coding sequence of known (MAP2K4) and suspected (YTHDF2) driver genes in breast cancer." (PMID 34158539, 2021). "Our findings revealed the downregulation of LINC01133 in ER+ breast cancer and provided novel insight to the role of METTL3/YTHDF2/LINC01133/IGF2BP2 axis in ER+ breast cancer, which might offer a novel perspective in the design and development of novel anticancer drugs." (PMID 40641925, 2025). "Similarly, studies in breast cancer reveal opposing functions of m6A regulators YTHDF2 and VIRMA." (PMID 39085650, 2024). "However, the impact of YTHDF2 on survival was conflicting in two independent breast cancer cohorts." (PMID 32986017, 2020). "Different from YTHDF2, the high expression of FTO significantly promotes the proliferation, invasion, and migration of breast cancer cells and reduces apoptosis." (PMID 40001550, 2025). "Our results revealed an increase in the m6A-binding ability of YTHDF2, and the KD of YTHDF2 noticeably increased the stability and expression of c-Myc and E2F1 transcripts in breast cancer cells." (PMID 41281757, 2025). "In breast cancer, METTL3 and YTHDF2 synergistically promote the degradation of LATS1 mRNA via the Hippo signaling pathway, enhancing tumor progression." (PMID 40761481, 2025). "FTO can reduce apoptosis of breast cancer cells and promote their growth by demethylating m6A in the 3′UTR of BNIP3 mRNA and inducing its degradation in a YTHDF2-independent manner." (PMID 40001550, 2025). "In breast cancer cells ALKBH5 overexpression erases m6A methylation from the GLUT4 mRNA, protecting it from YTHDF2‐mediated degradation and increases its expression through stabilizing the transcript." (PMID 39661414, 2024). "High levels of YAP/TAZ were found in the nucleus of breast cancer cells after inducing the expression of METTL3, while deleting the expression of YTHDF2 corrected such deviated expression in the nuclears." (PMID 36609396, 2023). "We demonstrated that Mettl3-mediated m6A methylation of LATS1 mRNA is recognized by YTHDF2, which reduces LATS1 expression and inactivates the Hippo pathway in breast cancer." (PMID 36609396, 2023). "Specifically, ALKBH5 removes the m6A modification of GLUT4 mRNA in cancer cells, and recruits YTHDF2 to combine with GLUT4 mRNA to enhance its stability, leading to increased glycolysis of breast cancer cells and resistance to HER2 targeted therapy." (PMID 37582735, 2023). "To determine the impact of YTHDF2 in breast cancer cells and understand its role in the m6A methylation of LATS1 mRNA in tumorigenesis and glycolysis, we altered the expression of YTHDF2 in breast cancer cells." (PMID 36609396, 2023). "Such m6A sites of LATS1 mRNA can be recognized by YTHDF2, which promotes the degradation of LATS1 mRNA and eventually tumorigenesis and glycolysis in breast cancer cells." (PMID 36609396, 2023). "METTL3 was identified as the m6A writer, with YTHDF2 as the reader protein of LATS1 mRNA, which plays a positive role in promoting both tumorigenesis and glycolysis in breast cancer." (PMID 36609396, 2023). "Knockout of the protein expression of METTL3 or YTHDF2 increased the expression of LATS1 mRNA and suppressed breast cancer tumorigenesis by activating YAP/TAZ in the Hippo pathway." (PMID 36609396, 2023). "In breast cancer, eight genes (METTL3, KIAA1429, ZC3H13, FTO, YTHDF1, YTHDF2, IGF2BP2, and IGF2BP3) were significantly enriched in tumor cells compared to immune or stromal cells." (PMID 35794212, 2022). "By comparing tumor and normal samples, we found that six proteins were differentially expressed in breast cancer significantly (P < 0.001), including EIF3A, HNRNPA2B1, HNRNPC, RBMX, YTHDF1, YTHDF2." (PMID 33585234, 2020).